STARD7 (StAR related lipid transfer domain containing 7)
Diseases named in the same sentence as STARD7 in open-access papers (continued):
Sharing a sentence is not in itself a finding about the gene and the disease.
preeclampsia (1 paper, 2013). Preeclampsia is a hypertensive disorder of pregnancy that is characterized by new-onset hypertension with proteinuria presenting after 20 weeks of gestation, and depending on mild or severe forms may initially present with severe headache, visual disturbances, and hyperreflexia. "Interestingly, StarD7 is a target gene of Has-miR-377, which is downregulated in the preeclamptic placenta, suggesting that StarD7 expression may be altered in preeclampsia." (PMID 23507753, 2013).
situs inversus (1 paper, 2022). A congenital condition in which there is complete right-to-left reversal of the position of the major thoracic and abdominal organs (that is, they are arranged in a mirror image of the normal positioning). "In 13 interrupted genes, CACNA1E (in case 12) and STARD7 (in case 17) are known causative and PDCL was found in subject (case 11) with situs inversus for the first time." (PMID 36186435, 2022).
triple-negative breast carcinoma (1 paper, 2025). An invasive breast carcinoma which is negative for expression of estrogen receptor (ER), progesterone receptor (PR), and human epidermal growth factor receptor 2 (HER2). "We demonstrate here that STARD7 is overexpressed in ERα+ breast malignancies and in Triple Negative Breast Cancers (TNBCs)." (PMID 40443279, 2025). "This conclusion was also true in triple negative breast cancer‐derived MDA‐MB231 cells lacking STARD7." (PMID 40443279, 2025). "Moreover, EGFR signaling is also impaired in triple negative breast cancer cells lacking STARD7, at least due to deregulated EGFR trafficking to lysosomes." (PMID 40443279, 2025).
cancer (5 papers, 2012 to 2026). A tumor composed of atypical neoplastic, often pleomorphic cells that invade other tissues. "Strikingly, despite generating similar molecular signatures, Stard7 deficiency inhibited tumor development in Azoxymethane (AOM)/Dextran Sulfate Sodium (DSS)-treated mice but promoted Wnt-driven cancer initiation in the intestine." (PMID 41912870, 2026). "Genome wide analysis has shown that the StarD7 transcript is altered in various conditions such as metabolic state, inflammation processes, cancer and behavior." (PMID 23507753, 2013). "Several genome wide analyses have shown that StarD7 is differentially expressed in various cell and tissue samples under different experimental conditions such as metabolic state, inflammation, cancer, and behavioral changes." (PMID 23507753, 2013). "Third, the StarD7 promoter is activated by the Wnt/β-catenin signaling pathway, which promotes proliferation and is frequently altered in cancer cells." (PMID 23507753, 2013). "Finally, StarD7 gene promoter is activated by Wnt/β-catenin signaling, a pathway that promotes proliferation and is frequently altered in cancer cells." (PMID 22952907, 2012). "The study also demonstrated a correlation between PARL or STARD7 expression and cancer cell resistance to the ferroptosis inhibitor protein GPX4, suggesting that targeting PARL or STARD7 could be a potential strategy to disrupt ferroptosis and provide novel approaches for anticancer therapies." (PMID 37548939, 2024).
tumor (5 papers, 2017 to 2026). "We next assessed the consequences of Stard7 deficiency in both Wnt-dependent tumor initiation and in inflammation-driven tumor development." (PMID 41912870, 2026). "To learn more on mechanisms through which lipid transfer proteins regulate tumor development, we first looked at the expression profile of STARD7 in human tumors." (PMID 40443279, 2025). "PARL and STARD7 may therefore represent promising targets to induce ferroptosis in tumours resistant to GPX4 inhibitors." (PMID 36658222, 2023). "Among the genes negatively regulated by KDM4B, STARD7, CPA4, FKBP14, and RNF6 have been shown to regulate cell proliferation and/or metastasis, whereas DYRK2 is a known tumor suppressor." (PMID 34766154, 2021).
STARD7 also shares sentences with these, for which no sentence is quoted: familial adult myoclonic epilepsy (3 papers); cervical squamous cell carcinoma (1); cholangiocarcinoma (1); colorectal tumor (1); diffuse large B-cell lymphoma (1); endocervical adenocarcinoma (1); epilepsy syndrome (1); Friedreich ataxia (1); Fuchs endothelial corneal dystrophy (1); glioblastoma (1); invasive carcinoma (1); Leukoencephalopathy (1); neurodegenerative disease (1); pancreatic adenocarcinoma (1); pancreatic cancer (1); rectum adenocarcinoma (1); skin cutaneous melanoma (1); spinocerebellar ataxia type 37 (1); temporal lobe epilepsy (1); testicular germ cell tumor (1); thymoma (1); Tremor (1).